MON1A (MON1 vesicular trafficking associated A)
Description:
Plays an important role in membrane trafficking through the secretory apparatus. Not involved in endocytic trafficking to lysosomes (By similarity). Acts in concert with CCZ1, as a guanine exchange factor (GEF) for RAB7, promotes the exchange of GDP to GTP, converting it from an inactive GDP-bound form into an active GTP-bound form.
Synonyms: SAND1; MGC13272
Tractability: PROTAC: ubiquitination databases record sites on it; its protein half-life has been measured.
Gene: Protein-coding gene on chromosome 3 (49,907,160 to 49,930,173, reverse strand). Ensembl gene ENSG00000164077.
Subcellular location (Human Protein Atlas): Cytosol
Pathways (Reactome):
Vesicle-mediated transport: RAB GEFs exchange GTP for GDP on RABs
Gene Ontology:
Molecular function: guanyl-nucleotide exchange factor activity; protein binding
Biological process: protein secretion; protein targeting to vacuole; vesicle-mediated transport
Cellular component: Mon1-Ccz1 complex; cytosol
Genetic constraint (gnomAD): Loss-of-function variants: 29 observed, 46.27 expected, observed/expected ratio (o/e) 0.63, 90% interval 0.47 to 0.85. The upper end of that interval is the gene's LOEUF score, 0.85, which puts it in group 3 of 6, group 1 being the genes least tolerant of losing a copy. Missense variants: 615 observed, 791.45 expected, observed/expected ratio (o/e) 0.78, 90% interval 0.73 to 0.83. Synonymous variants: 275 observed, 333.84 expected, observed/expected ratio (o/e) 0.82, 90% interval 0.75 to 0.91.
Homologues: Orthologues: chimpanzee MON1A (100% identical), macaque MON1A (98% identical), dog MON1A (97% identical), rabbit MON1A (97% identical), pig MON1A (97% identical), rat Mon1a (94% identical), mouse Mon1a (94% identical), guinea pig MON1A (94% identical), tropical clawed frog mon1a (63% identical), zebrafish mon1a (58% identical), Drosophila melanogaster Mon1 (37% identical), Caenorhabditis elegans sand-1 (23% identical). Paralogues in human: MON1B (42% identical).
Diseases named in the same sentence as MON1A in open-access papers:
MON1A is named in the same sentence as 9 diseases in open-access papers, as found by Europe PMC text mining. Sharing a sentence is not in itself a finding about the gene and the disease. The quoted sentences say what the papers report.
ovarian carcinoma (1 paper, 2023). A malignant neoplasm originating from the surface ovarian epithelium. "The expression of FLVCR2 and SLC40A1 involved in iron export was associated with improved OS in ovarian cancer, while the expression of MON1A in this process was associated with poor OS in ovarian cancer." (PMID 38186569, 2023). "Similarly, most genes involved in iron export, such as SLC40A1, FLVCR1, ABCG2, and MON1A, displayed reduced expression in ovarian cancer tissues; in contrast, only one gene, FLVCR2, showed the opposite trend." (PMID 38186569, 2023).
infection (1 paper, 2023). The state of being infected such as from the introduction of a foreign agent such as serum, vaccine, antigenic substance or organism. "The knockout of any of these proteins lead to an important drop in infection (89.4% for MON1A and 82.4% for MON1B), also partially recovered when the cells are transcomplemented." (PMID 37880247, 2023). "Because CCZ1 is in complex with MON1 (itself formed by MON1A and MON1B), we knocked out MON1A and MON1B respectively and assessed for infection with VSVΔG/MARVGP." (PMID 37880247, 2023).
tumours (1 paper, 2017). "The most common 44 genes (p<0.001) including VHL enlist MON1A, CCDC51 and TMA7 at 3p21.31 (31/29 HRO tumours), and MIRLET7G and WDR28 at 3p21.1 (31/31 tumours), respectively." (PMID 28486536, 2017).
MON1A also shares sentences with these, for which no sentence is quoted: Alzheimer disease (1 paper); Failure to thrive (1); Insulin resistance (1); ischemic stroke (1); memory impairment (1); schizophrenia (1).